FAP (fibroblast activation protein alpha)
Diseases named in the same sentence as FAP in open-access papers (continued):
Sharing a sentence is not in itself a finding about the gene and the disease.
cancer (continued). "Compared with GIN and normal tissue samples, both the percentage of positive cells and the average fluorescence intensity of FAP positive cells were significantly increased in cancer tissues (all P < 0.05, with one-way ANOVA)." (PMID 36401232, 2022). "Extensive emerging data implicate FAP-positive cells as important accomplices involved in cancer progression and metastases." (PMID 34740953, 2022). "Small-molecule FAP inhibitors (FAPIs) have also been discovered and conjugated with radioactivity to yield excellent imaging agents suitable for a variety of cancer indications." (PMID 34168013, 2022). "Two cancer-associated fibroblast markers—the alpha-smooth muscle actin (α-SMA) and fibroblast activation protein alpha (FAP)—were also determined in the two adenocarcinomas." (PMID 36290310, 2022). "Other studies also reported a positive correlation between macrophages which expressed markers of M2 macrophages (e.g., CD163, DC-SIGN) or cancer-associated fibroblasts which expressed FSP1, FAP, and poor outcome for CRC patients." (PMID 35365629, 2022). "Another clinical trial (NCT04499365) plans to enroll 500 patients for 68Ga-FAPI-04 PET to provide robust clinical data regarding the use of FAP-targeted imaging to diagnose and monitor cancer." (PMID 35626272, 2022). "In this context, it has been established that FAP is expressed predominantly in stromal cells, whereas only very low levels of expression are detected in cancer cells in resected pancreatic ductal adenocarcinoma (PDAC) tissues." (PMID 36263225, 2022). "Among these, there is growing interest in the role of CXCL12, CXCR4, and FAPα expression in cancer because of their immunosuppressive and procancer properties 50-52." (PMID 34976180, 2022). "The analysis of continuous mfIHC variables in MRI true-positive cancer lesions showed that both a higher stromal fraction of FAP-positive cells and a lower stromal fraction of SMA-positive cells predicted earlier BCR." (PMID 36874403, 2022). "FAP has recently emerged as one of the most promising target structures for molecular imaging and therapy in cancer." (PMID 34957527, 2022). "Fibroblast activation protein (FAP) is a serine protease expressed in activated fibroblasts that infiltrate tumors and provide support for cancer cells." (PMID 35626272, 2022). "Analysis of populations of cells sorted from cancer tissue revealed the Fibroblast Activation Protein (FAP)-positive CAF population to be the predominant source of ADAM12 expression." (PMID 35413826, 2022). "FAP expression analysis was performed by immunohistochemistry and autoradiography on primary human cancer specimens." (PMID 35608703, 2022). "The cancer-associated fibroblasts accelerate the proliferation, metastasis, and invasion of cancer cells and are activated by surface fibroblast activation protein (FAP) expression and TGF-β cytokine and vascular epithelial growth factor secretion." (PMID 35745775, 2022). "PAAD is histologically characterized by a large stroma volume, and previous studies have consistently reported the suppression of intra-tumoral effector T-cells by the FAP-expressing stromal cells among different cancer types." (PMID 36263225, 2022). "As a type II transmembrane protein expressed in activated fibroblasts, fibroblast activation protein (FAP) is highly overexpressed in a variety of malignant tumors and is related to poor prognosis, indicating that FAP is a potential target for PET imaging." (PMID 36275809, 2022). "By examining the differential expression between cancer and normal samples, we observed that the expression level of FAP was generally lower in normal samples compared to tumors across these cancer types." (PMID 35359436, 2022). "Multiple studies have shown that FAP expression level is elevated in esophageal, colorectal, pancreatic, and breast cancers and has a role in promoting cancer progression." (PMID 35186170, 2022).
cancer (continued). "Fibro_2 cells were characterized by collagen (COL1A1, COL3A1) and cancer-associated fibroblast genes (CTHRC1, FAP)." (PMID 35935940, 2022). "Spearman’s relation was conducted to analyze the association between FAP expression and TMB for each cancer type separately." (PMID 35359436, 2022). "While typically low to undetectable in most normal adult tissues, FAP is highly expressed on the cell surface in multiple cancer subtypes." (PMID 35608703, 2022). "The fibroblast activation protein (FAP) is an emerging target for molecular imaging and therapy in cancer." (PMID 34957527, 2022). "Regarding CAFs, recently, there is a relatively high nuclear research output and the FAP-targeting radioligands are extremely promising for pan-cancer nuclear imaging." (PMID 35788730, 2022). "To take advantage of the favorable properties of heterodimers, we designed and synthesized bispecific heterodimer radiotracers targeting both PSMA and FAP for cancer imaging." (PMID 35337180, 2022). "Previous studies have shown that CAF upregulation of FAP drives cancer progression and invasion by affecting ECM remodeling, immunosuppression, EMT, angiogenesis, and intracellular signaling." (PMID 35359436, 2022). "The implementation of the [18F]AlF radiolabelling method in the development of FAP-targeted theranostics reflects the relevance of this radiochemical approach for the benefit of cancer patients." (PMID 35471681, 2022). "Prostate-specific membrane antigen (PSMA) is expressed in a variety of cancer cells, while the fibroblast activation protein (FAP) is expressed in the microenvironment of tumors." (PMID 35456554, 2022). "FAP-targeted radiopharmaceuticals represent a breakthrough in cancer imaging and a viable option for therapeutic applications." (PMID 36015106, 2022). "Different markers, such as a-SMA, FAP, PDGFR-β, periostin, have been used for the detection of cancer-associated fibroblasts (CAFs)." (PMID 36139552, 2022). "Their promising pharmacokinetics warrant further investigations toward clinical translation for the treatment of FAP-positive cancers." (PMID 34593598, 2022). "Although there was variability in the intensity and frequency of FAP expression, FAP was positive in more than 50% of cases from 11 of 14 cancer types." (PMID 34740953, 2022). "Although FAP expression is high in cancer stroma, it is considerably low in normal adult tissues, except for sites of active tissue damage, chronic inflammation, and remodeling." (PMID 35202189, 2022). "Here, we first screened TMAs from 14 cancers for FAP expression to guide patient selection for the exploratory imaging trial." (PMID 34740953, 2022). "Recently, a variety of quinolone-based FAP inhibitor (FAPI) radiopharmaceuticals has been developed and demonstrated excellent uptake in different FAP-positive tumors of cancer patients." (PMID 34593598, 2022). "We observed increased plasma cell proportions in diffuse-type tumors associated with epithelial-resident KLF2 and stage-wise accrual of cancer-associated fibroblast subpopulations marked by high INHBA and FAP coexpression." (PMID 34642171, 2022). "FAP has been identified in a wide range of cancer types and shows minimal expression in normal tissues." (PMID 35719937, 2022). "The patients who had high expression of FAP were correlated with an aggressive phenotype of cancer, metastasis, and shorter survival than patients with low FAP expression." (PMID 36616017, 2022). "In several cancer types, high FAP expression is related to poor prognosis, indicating a possible predictive value." (PMID 36428657, 2022). "Anti-FAP antibody sibrotuzumab labeled with 131Iodine has been reported for the treatment of patients with metastasized FAP-positive carcinomas in a phase I dose-escalation study." (PMID 35326670, 2022). "In the first pattern, FAPα was mainly stained in carcinoma cells and staining in TIICs was insignificant." (PMID 34976180, 2022).
cancer (continued). "Fibroblast activation protein (FAP) is overexpressed in the CAFs in numerous epithelial carcinomas and weakly expressed in healthy tissues; therefore, FAP represents an attractive target for theranostics." (PMID 36182995, 2022). "Although normal fibroblasts expressed FAP mildly, fibroblasts stimulated with cancer medium, CAFs, exhibited strong FAP expression (green) mainly on the cell surface, whereas α-SMA (red) was strongly expressed mainly in the cytoplasm." (PMID 33462372, 2021). "PET imaging of the fibroblast activation protein (FAP) expression in cancer was recently introduced." (PMID 34137945, 2021). "The cancer-related overexpression of FAP and the significant role of CAFs in tumoral progression development of FAP inhibitors (FAPI) for cancer treatment and successively for theranostic application were logical conclusions." (PMID 33925632, 2021). "This review provides an overview of the state of the art in TME compositions, particularly CAFs and FAP, and their roles in cancer biology." (PMID 34681246, 2021). "More efforts have been made to identify novel substrates of FAP to clarify more detailed functions of FAP in cancers." (PMID 34068501, 2021). "The resource, in this case, is the diffusible factor fibroblast activation protein-α (FAP) that improves cancer fitness, while the cost is the effort of producing and excreting it to the medium." (PMID 34359555, 2021). "Prolyl endopeptidase FAP reduces scar resolution, activating plasmin inhibitors and blocking fibrinolysis, though questions remain regarding its role in cancer." (PMID 34641541, 2021). "Fortunately, technological advances over the past years are opening new opportunities in understanding the complex biology of CAFs in cancer and will pave the way for new targets that can be used in future developments, one of those targets being FAP." (PMID 33806468, 2021). "FAP expression is high in activated stromal fibroblasts at sites of tissue remodeling and can also be expressed in some cancer cells such as sarcoma." (PMID 33669804, 2021). "In a recent analysis, Solano-Itturi and colleagues investigated the effect of fibroblast activation protein-α (FAP) expression on development of early metastases and cancer specific survival." (PMID 33886004, 2021). "FAP is a cell-surface protease, and the protein was named for its prevalence on reactive fibroblast cells, particularly in different types of cancer." (PMID 34771664, 2021). "Microenvironmental biomarkers such as CD8 and FAP have shown clinical utility in a variety of cancers, including melanoma and breast cancer." (PMID 34771664, 2021). "As compared with peri-cancerous fibroblasts and normal fibroblasts, the cancer associated fibroblasts showed increased expression of alpha SMA and FAP." (PMID 34405010, 2021). "Our study revealed that the new HNav-FAP provided selective targeting of FAP-overexpressing fibroblasts over cancer cells and proved more effective in killing target fibroblasts compared to non-functionalized drugs." (PMID 33562504, 2021). "FAP expression levels have been found to correlate with poor disease prognosis in several types of cancer, including colon, pancreatic, and hepatocellular carcinoma." (PMID 33806468, 2021). "FAP-directed PET has been introduced for imaging FAP expression of cancer and its stromal microenvironment." (PMID 33669804, 2021). "Current studies provide evidence that FAP can participate in complex processes that drive and maintain the progression of malignant tumors." (PMID 33494271, 2021). "Positron emission tomography (PET) imaging of fibroblasts is gaining interest in the oncology community, with recent advent of FAP-targeted radiotracers, a versatile theranostic in multiple cancers 14-16." (PMID 34335962, 2021). "The functions of FAP in cancer are incompletely understood and seem very probably different in different cell types." (PMID 33494271, 2021).
cancer (continued). "Following this study FAP+ CAFs have been extensively investigated and many pre-clinical studies have demonstrated the potential for depleting these cells in cancer treatment." (PMID 34262652, 2021). "Although the biological mechanism of FAP on cancer prognosis is still vague and inconsistent throughout reports in the literature, the existence of FAP in malignant stroma is determinative as a promising target for cancer imaging and therapy." (PMID 34681246, 2021). "This review discusses the basic biological characteristics of FAP and its applications in the diagnosis and treatment of various cancers." (PMID 34490078, 2021). "Fibroblast activation protein (FAP) is highly expressed in many human cancers and can be targeted by quinoline-based FAP inhibitors (FAPIs)." (PMID 34436693, 2021). "Recently, researchers at the University of Heidelberg have introduced PET imaging for FAP expression in cancer, producing radiopharmaceuticals derived from quinoline peptidomimetics that bind with high affinity to FAP expressed on CAFs labeled with [68Ga]." (PMID 34572771, 2021). "The expression of FAP has been found to promote immunosuppression and worse outcomes for patients with several types of cancers." (PMID 34771664, 2021). "In this review, we aim to provide a comprehensive overview of the biological functions and fates of TME, CAFs, and FAP in cancer prognosis and development." (PMID 34681246, 2021). "A recent study has shown promising results in the visualization of cancer-associated fibroblasts (CAF) with the use of the quinoline-based PET tracers, which act as FAP inhibitors (FAPI), namely the 68Ga-FAPI." (PMID 34298967, 2021). "These particles can hold drugs or fluorescent dyes and can release loaded drugs and fluorescent dyes under the action of FAP endonuclease, so they can be used as drug delivery platforms and cancer tissue imaging tools." (PMID 34490078, 2021). "FAP is a fibroblast activating protein, which has found to be involved in the growth and formation of a variety of cancers." (PMID 35004767, 2021). "Taken together, it has been proven that FAP is a potential target for cancer diagnostics and therapeutics." (PMID 33996747, 2021). "The last type of tracer targets fibroblast activation protein (FAP inhibitor), which is expressed by CAF (cancer-associated fibroblast)." (PMID 34944781, 2021). "As FAP is only overexpressed by activated fibroblasts, it is likely that CAFs play a major role in cancer growth." (PMID 34638433, 2021). "Alpha-smooth-muscle actin (αSMA) and fibroblast activation protein (FAP) are CAF markers in the stroma of cancer tissues, and their expression intensity correlates with tumor infiltration, lymph node metastasis, and poor prognosis." (PMID 34445235, 2021). "Functionalized nanocages (HFn-FAP) have significantly higher binding with FAP+ CAFs than with FAP− cancer cells." (PMID 33562504, 2021). "Head and neck cancers are among the most investigated cancers as a target of FAP-directed PET imaging." (PMID 34858834, 2021). "being stable, its significant non-specific uptake in the liver and intestines poses a challenge in detecting the abdominal FAP-positive lesions in cancer patients." (PMID 35071007, 2021). "Being the predominant component of cancer stroma in most types of cancer, FAP can therefore be considered a significant target for therapeutic intervention, which will be discussed in later sections." (PMID 33806468, 2021). "FAP is a very closely related enzyme to DPP-4 and exhibits higher levels in some cancers, especially in cancer-associated fibroblast." (PMID 34063285, 2021). "myCAF activity is dependent on cancer cell contact so they are located adjacent to cancer cells, especially ones that co-express high levels of αSMA and FAP." (PMID 33499238, 2021). "The phenotype of FAP+ mesenchymal cell cultures isolated from GBMs is similar to cancer-associated fibroblasts (CAF), which represent the main subpopulation of FAP+ stromal cells in carcinomas." (PMID 34282761, 2021).
cancer (continued). "The overexpression of FAP in CAFs can organize fibronectin and collagen I fibers into parallel orientation, which can elevate directionality and velocity of cancer cells in the ECM." (PMID 34852849, 2021). "Although there is emerging FAP-targeted PET/CT data available for cancer imaging, activated fibroblasts, particularly in tissue-remodeling processes, can also express FAPs." (PMID 34858834, 2021). "Chimeric antigen receptor (CAR) T cell therapy is one of the most popular immunotherapies, and FAP has been investigated as a target for cancer cell recognition." (PMID 34068501, 2021). "While most of the existing literature has been focussed on the application of FAP-specific PET in various kinds of cancers, some researchers have, both intentionally or unintentionally, used FAP-specific PET in patients with non-cancerous diseases." (PMID 33606104, 2021). "Although radiolabeled FAP inhibitors proved to be successful in enabling the imaging of multiple human cancers, the time-dependent clearance from tumors seems to currently limit their utility as FAP-targeted radiotherapeutics." (PMID 34681246, 2021). "Recently, the development of several small-molecule FAP inhibitors for radiolabeling with 68Ga has resulted in the emergence of studies evaluating its clinical role in cancer imaging." (PMID 34858834, 2021). "Targeting CAFs can be achieved on different ways, among other things by targeting the fibroblast activation protein (FAP) which is significantly overexpressed by CAFs of numerous cancer types compared to healthy tissue." (PMID 33925632, 2021). "Based on current reports, FAP imaging with 68Ga-labeled FAPI PET/CT appears to be a promising strategy for the visualization of several cancers." (PMID 34681246, 2021). "To examine the ability of FAPVap to measure FAP expression on cancer cells in the living brain, we tested the probe on a xenograft model." (PMID 34931988, 2021). "Although the clinical studies are currently in the early stage and prospective studies are ongoing, it is evident that FAP is a highly promising target for cancer imaging and therapy." (PMID 34681246, 2021). "FAP expression has been observed in the activated stromal fibroblasts of more than 90% of all human carcinomas, with elevated levels of stromal FAP predicting a poor survival outcome." (PMID 34200480, 2021). "Fibroblast activation protein (FAP) is overexpressed by CAFs of several cancer entities, including HNCs and on the other hand, FAP expression in healthy tissue is relatively low." (PMID 32447444, 2020). "FAP has been mainly described in activated fibroblasts from cancer, chronic inflammatory and fibrotic lesions." (PMID 32428869, 2020). "This was demonstrated in BCa as well, as healthy recipient fibroblasts gained malignant phenotypes and transformed into cancer associated fibroblasts (SMA, FAP, galectin), after exposure to cancer cell-derived EVs." (PMID 32485907, 2020). "In more than 90% of human cancers, fibroblast activation protein (FAP) is highly expressed in activated stromal fibroblasts, responsible for myofibroblast recruitment, differentiation, and proliferation." (PMID 33158289, 2020). "The purpose of this systematic review is to summarize the findings of using fibroblast activation protein (FAP) as a new tracer for positron emission tomography (PET) in cancer patients." (PMID 32942573, 2020). "Examples of ongoing CAF anti-cancer therapy include CAF specific depletion with anti-FAP antibodies, maintaining CAFs in a quiescent state with Vitamin D or Retinoic Acid, or targeting CAF signaling pathways involved in matrix remodeling." (PMID 32384738, 2020). "In a publication by the same group on patients with inconclusive FDG PETs, FAP-specific PET detected an occult esophageal primary in a patient whose cancer was formerly classified as CUP." (PMID 32942573, 2020). "FAP has also been discussed in reports from studies where it is used as a target for cancer treatments using CAR T cells." (PMID 32858947, 2020).